GATC (glutamyl-tRNA amidotransferase subunit C)
Description:
Allows the formation of correctly charged Gln-tRNA(Gln) through the transamidation of misacylated Glu-tRNA(Gln) in the mitochondria. The reaction takes place in the presence of glutamine and ATP through an activated gamma-phospho-Glu-tRNA(Gln).
Synonyms: 15E1.2; FLJ37000; COXPD42
Tractability: No criterion of Open Targets' tractability assessment is met for any kind of drug.
Gene: Protein-coding gene on chromosome 12 (120,446,444 to 120,463,749, forward strand). Ensembl gene ENSG00000257218.
Subcellular location: Mitochondrion
Gene Ontology:
Molecular function: protein binding; glutaminyl-tRNA synthase (glutamine-hydrolyzing) activity
Biological process: glutaminyl-tRNAGln biosynthesis via transamidation; mitochondrial translation; regulation of translational fidelity
Cellular component: glutamyl-tRNA(Gln) amidotransferase complex; mitochondrion
Genetic constraint (gnomAD): Loss-of-function variants: 8 observed, 10.03 expected, observed/expected ratio (o/e) 0.8, 90% interval 0.47 to 1.43. The upper end of that interval is the gene's LOEUF score, 1.43, which puts it in group 5 of 6, group 1 being the genes least tolerant of losing a copy. Missense variants: 170 observed, 157.99 expected, observed/expected ratio (o/e) 1.08, 90% interval 0.95 to 1.22. Synonymous variants: 67 observed, 71.49 expected, observed/expected ratio (o/e) 0.94, 90% interval 0.77 to 1.15.
Homologues: Orthologues: chimpanzee GATC (99% identical), macaque GATC (99% identical), rabbit GATC (88% identical), dog GATC (84% identical), pig GATC (84% identical), guinea pig GATC (76% identical), mouse Gatc (74% identical), rabbit GATC (71% identical), zebrafish gatc (51% identical), tropical clawed frog GATC (50% identical), rat Gatc (49% identical), Drosophila melanogaster GatC (34% identical), and 1 more.
Diseases named in the same sentence as GATC in open-access papers:
GATC is named in the same sentence as 2 diseases in open-access papers, as found by Europe PMC text mining. Sharing a sentence is not in itself a finding about the gene and the disease. The quoted sentences say what the papers report.
infection (2 papers, 2020 to 2025). The state of being infected such as from the introduction of a foreign agent such as serum, vaccine, antigenic substance or organism. "Inhibition of GatC can effectively prevent infection by halting bacterial proliferation." (PMID 40248715, 2025). "As expected, the infection of A. castellanii with noumeavirus, which do not encode the GATC R-M system, do not alter its DNA." (PMID 32461636, 2020).
GATC also shares sentences with these, for which no sentence is quoted: lactic acidosis (1 paper).